INS (insulin)
Diseases named in the same sentence as INS in open-access papers (continued):
Sharing a sentence is not in itself a finding about the gene and the disease.
Hyperglycemia (continued). "Glucolipotoxicity, a key mechanism in β-cell dysfunction, refers to the synergistic toxic effects of chronic hyperglycemia and elevated free fatty acids on pancreatic β-cells, ultimately leading to impaired insulin secretion and β-cell apoptosis." (PMID 40002577, 2025). "Recent advancements, such as the iLet Bionic Pancreas, represent major breakthroughs; however, limitations regarding postprandial hyperglycaemia persist due to delayed insulin absorption." (PMID 40718205, 2025). "In humans, CERS6, the primary enzyme responsible for synthesizing C14–C16 ceramides, correlates with BMI, hyperglycemia, and decreased insulin sensitivity." (PMID 41278909, 2025). "Another study showed that in the hyperglycemia rat model with uricase gene knockout, the blood glucose of rats increased, which led to decreased insulin/glucose ratio." (PMID 40710003, 2025). "More recently, the idea of a Gαs-Gαq switch has been proposed, describing how the GLP-1R adapts to chronic hyperglycemia by preferentially coupling to Gαq to support insulin secretion." (PMID 40526441, 2025). "The male and female offspring of mothers who consumed a HF diet during pregnancy overall displayed reduced insulin responses, but this effect was only significant in the offspring additionally exposed to maternal hyperglycaemia." (PMID 40021748, 2025). "The patient was admitted to a special care unit and started on continuous intravenous (IV) infusion of potassium chloride (KCL) at 8 mEq/hour and insulin infusion as per hospital protocol for hypokalemia and hyperglycemia, respectively." (PMID 40270995, 2025). "Specifically, acute hyperglycemia stimulates substantial insulin secretion from pancreatic β-cells, and this insulin surge can trigger several adverse consequences." (PMID 41463929, 2025). "Females fed with HFD display less severe impairments in insulin sensitivity, hyperglycemia, and overall glycemic control than males after 10 weeks, and even more markedly after 35 weeks of HFD diet consumption." (PMID 41550876, 2025). "As phenotype analysis suggested the correlation of Cgref1 with hyperglycemia and undermined glucose homeostasis, we decided to compare insulin-mediated glucose uptake between WT and Cgref1-/- mice." (PMID 40303310, 2025). "As a result of STZ injection in rats, we observed the typical signs of hyperglycaemia: the blood glucose and glycated haemoglobin levels significantly increased, and insulin content and animal body mass considerably decreased." (PMID 40161891, 2025). "In summary, the results presented here emphasize the importance of Gαs signaling through cAMP as having more than simply a modulatory function on insulin secretion, but it is also essential for the stimulated responses that control hyperglycemia." (PMID 40526441, 2025). "Management prioritizes aggressive fluid resuscitation, insulin therapy to correct hyperglycemia and reduce triglyceride levels, and electrolyte monitoring." (PMID 41262426, 2025). "Our results show that the animals that were malnourished during adolescence presented a greater tolerance to glucose, as well as a greater peripheral sensitivity to insulin, in both sexes, although the males had fasting hyperglycemia at 120 days of age." (PMID 41154756, 2025). "The Society of Critical Care Medicine recommended initiating insulin therapy when blood glucose levels reach 150 mg/dL, and an updated guideline suggested treating persistent hyperglycemia using a threshold of 180 mg/dL." (PMID 40607229, 2025). "SMBG offers patients immediate blood glucose readings at specific time points, enabling prompt adjustments to diet, exercise, or insulin dosage to maintain glucose levels within a safe range and prevent hypoglycemia or hyperglycemia." (PMID 40053775, 2025). "These cases have hyperglycemia and high HbA1c levels and require insulin therapy at onset due to decreased insulin secretory ability, but insulin therapy often becomes unnecessary later." (PMID 40406776, 2025).
Hyperglycemia (continued). "The reversal of this translocation by pA1c®HI suggests that the postbiotic mitigates the detrimental effects of hyperglycemia, helping to maintain insulin signaling and metabolic homeostasis." (PMID 40869412, 2025). "Such errors can lead to improper insulin dose adjustments, resulting in either hypoglycemia or hyperglycemia." (PMID 41049880, 2025). "Blood insulin levels in pregnant women with hyperglycemia are usually high, which can promote increased renal sodium reabsorption and increased blood volume." (PMID 40589878, 2025). "STZ targets pancreatic β‐cells, permanently impairing insulin secretion, while a low dose induces mild hyperglycaemia." (PMID 41017344, 2025). "Sulfonylureas were used in 17% of HNF1A-MD patients and in 6% of GCK-hyperglycemia patients; all of whom were switched to insulin during pregnancy." (PMID 41409604, 2025). "Its context-dependent duality, promoting glucose release in hypoglycemia and insulin sensitivity in hyperglycemia, highlights a unique regulatory role." (PMID 41438219, 2025). "The resulting oxidative stress impairs insulin secretion, contributing to chronic hyperglycemia and further ROS accumulation—establishing a vicious cycle." (PMID 41154538, 2025). "This reduction can be attributed to the advanced algorithms in AID systems, which continuously monitor glucose levels and adjust insulin delivery in real-time, thereby preventing prolonged periods of hyperglycaemia and maintaining tighter glycaemic control." (PMID 39792171, 2025). "STZ selectively damages insulin-producing β cells in the pancreas, leading to reduced insulin secretion and hyperglycemia." (PMID 39846251, 2025). "Followed by high serum insulin levels, hyperglycemia can induce the proliferation of cancer cells (glucose-hungry cells) through different mechanisms, consequently supporting tumor cell growth." (PMID 40149994, 2025). "During the third trimester, apart from one woman from the GCK-hyperglycemia group treated with basal insulin only, all patients were treated with basal-bolus insulin therapy." (PMID 41409604, 2025). "Thiscondition, where insulin effectiveness is diminished but glucose levelsare maintained by compensatory production, characterizes the initialphases of insulin resistance, preceding pancreatic exhaustion andovert fasting hyperglycemia." (PMID 40852283, 2025). "A major methodological challenge in T2DM is the potential confounding influence of chronic hyperglycemia, exogenous insulin therapy, and oral hypoglycemic agents, including secretagogues and insulin sensitizers, on conventional insulin resistance indices." (PMID 41585795, 2025). "She required inpatient admission because of worsening symptoms, and work-up revealed severe hypokalemia and hyperglycemia requiring intravenous (IV) potassium chloride and IV insulin." (PMID 40270995, 2025). "As a consequence, a switch from aerobic to anaerobic metabolism and acidosis follows, which is clinically reflected by elevated serum lactate and free fatty acids and is promoted by decreased insulin secretion and hyperglycemia." (PMID 40141360, 2025). "Autoantibodies targeting cytoplasmic components of pancreatic islets—such as glutamic acid decarboxylase (GAD), insulin, and tyrosine phosphatase proteins (IA-2/IA-2β)—can be detected months to years before the onset of hyperglycemia." (PMID 40906116, 2025). "PPAR agonists activate PPARA and/or PPARG receptors, improving inflammation, insulin sensitivity, hyperglycemia, and hyperlipidemia, which are the hallmarks of T2DM." (PMID 41011980, 2025). "This pathway emphasizes the correlation between increased antioxidant enzyme activity, improved insulin signaling, and reduced hyperglycemia after agmatine treatment." (PMID 40722940, 2025). "In GDM, hyperglycaemia impairs the ability of β‐cells to sense glucose and release insulin (β‐cell dysfunction), leading to a progressive failure to compensate for peripheral insulin resistance, which in turn worsens hyperglycaemia." (PMID 41017344, 2025).
Hyperglycemia (continued). "Maternal hyperglycemia stimulates an increase in fetal insulin production and fat storage, leading to macrosomia." (PMID 40375950, 2025). "Hyperglycemia-induced production of reactive oxygen species (ROS) can impair pancreatic β-cell function and promote insulin resistance in peripheral tissues." (PMID 40563357, 2025). "We also measured sVAP-1, since its semicarbazide-sensitive amine oxidase (SSAO) activity generates methylglyoxal, and hyperglycemia-induced VAP-1 produces H2O2 with insulin-sensitizing effects." (PMID 41305664, 2025). "GLP-1 is a naturally occurring small molecule peptide that promotes insulin release in hyperglycemia." (PMID 40224490, 2025). "Reduced insulin signaling can disrupt glucose metabolism, leading to hyperglycemia and increased the production of reactive oxygen species (ROS), thereby inducing oxidative stress." (PMID 40729004, 2025). "These hormonal shifts drive metabolic changes: cortisol increases hepatic gluconeogenesis and antagonizes insulin, leading to hyperglycemia." (PMID 40806903, 2025). "These compounds influence multiple molecular targets, regulating critical pathways that enhance β-cell proliferation, stimulate insulin secretion, reduce β-cell apoptosis, and alleviate hyperglycemia by optimizing glucose metabolism in the liver." (PMID 40143095, 2025). "Due to the research and clinical focus on hyperglycemia in sepsis, strict glucose control using insulin was formerly the standard of care." (PMID 39753379, 2025). "Low‐dose STZ injections resulted in β‐cell ablation in the pancreas, leading to dysfunction in compensatory insulin secretion and resultant hyperglycemia in the animals." (PMID 40905109, 2025). "Inhibiting, PI3K blocks this process, resulting in a dose-dependent increase in plasma fasting C-peptide and insulin, leading to systemic hyperglycemia." (PMID 40386392, 2025). "In this pragmatic study of 103 critically ill patients receiving insulin for hyperglycaemia, we found that tissue glucose measurements had a bias of −0.30 mmol/L." (PMID 41146739, 2025). "In GCK-hyperglycemia, the need for higher total daily insulin doses — despite suboptimal HbA1c in the second trimester — highlights physiological resistance to insulin therapy due to homeostasis and supports the use of tailored approaches." (PMID 41409604, 2025). "In the American Association of Clinical Endocrinologists (AACE)/American College of Endocrinology (ACE) comprehensive T2DM 2017 management algorithm, insulin is recommended for T2DM patients presenting with symptoms of hyperglycaemia and an HbA1c > 9.0%." (PMID 40482054, 2025). "This initial reduction in nutrient absorption helps blunt postprandial hyperglycemia and lowers circulating insulin levels, thereby improving insulin sensitivity." (PMID 40864811, 2025). "It occurs due to an insufficient supply of insulin, leading to metabolic acidosis, excessive ketone body production and uncontrolled hyperglycemia." (PMID 41149081, 2025). "Women with fasting or combined hyperglycemia (groups A and C) were more likely to receive insulin therapy compared to group B (88.4 and 81.3% vs. 49.3%, p < 0.001)." (PMID 40569563, 2025). "Recombinant SPARCL1 protein induces fasting hyperglycemia, hyperinsulinemia, and worsens insulin sensitivity in HFHC diet-fed mice." (PMID 40243151, 2025). "In both forms, the decrease in inefficient beta cell mass plays a vital role, leading to insufficient insulin synthesis and ensuing hyperglycemia." (PMID 40913218, 2025). "This phase is further classified into three stages: Stage 1, defined by normoglycaemia; Stage 2, characterized by dysglycaemia; and Stage 3, marked by hyperglycaemia, which typically presents clinically and necessitates insulin therapy." (PMID 40134221, 2025). "It is regarded as a chronic metabolic disturbance that is unfortunately on the rise and is distinguished by hyperglycemia due to inadequate insulin production, altered insulin action, or a combination thereof." (PMID 39861406, 2025).
Hyperglycemia (continued). "These systems can automatically adjust insulin infusion based on real-time glucose readings, suspending or increasing insulin delivery in response to hypoglycemia or hyperglycemia." (PMID 40217595, 2025). "GLP−1 receptor agonists (including liraglutide and semaglutide) improve neuronal insulin resistance by enhancing insulin-sensitive glucose utilization and inhibiting yeast fluke driven by hyperglycemia." (PMID 41332987, 2025). "These medications can significantly alter blood glucose levels either directly (e.g., insulin therapy) or indirectly (e.g., steroids inducing hyperglycemia)." (PMID 40225322, 2025). "This progressive metabolic disorder is characterized by the dysregulation of glycemic homeostasis, leading to chronic hyperglycemia secondary to defects in insulin secretion, insulin resistance, or the coexistence of both processes." (PMID 41255523, 2025). "The integrated Model Predictive Control (MPC) algorithm is able to adjust basal insulin delivery and to deliver a correction bolus in case of hyperglycaemia every hour." (PMID 40642512, 2025). "The patient required frequent insulin dose adjustments due to this paradoxical combination of persistent hyperglycemia and intermittent hypoglycemia." (PMID 41040769, 2025). "Prior to that, she used inhaled insulin (Afreeza®) at least once daily to help resolve post-prandial hyperglycemia, which was later denied by her insurance." (PMID 39707844, 2025). "Hyperglycemia usually results from varying peripheral resistance to insulin action, defective insulin secretion, and disease complications." (PMID 40371362, 2025). "To emphasize, insulin is a peptide hormone secreted by pancreatic beta cells in response to hyperglycemia." (PMID 40430851, 2025). "This explains the observed MSG-induced hyperglycemia and dyslipidemia, suggesting a possible defect in insulin sensitivity." (PMID 40407528, 2025). "At its core lies an imbalance in insulin production or action, leading to sustained hyperglycemia and progressive multi-organ dysfunction." (PMID 41404505, 2025). "We believed that such hyperglycemia was entirely avoidable if continuous monitoring of glucose and insulin injection were proceeded as advised." (PMID 40115026, 2025). "Current treatments aim to prevent β-cell deterioration by promoting improved insulin function and/or enhancing pancreatic function to avoid the development of hyperglycemia." (PMID 41155548, 2025). "Chronic treatment with Hsp90 inhibitors in obese or diabetic mouse models activates the Hsf1–Hsp70 stress pathway, leading to improved glucose control, reversal of hyperglycemia, and enhanced insulin sensitivity." (PMID 41226319, 2025). "Hyperglycemia also accelerates the formation of advanced glycation end-products (AGEs), leading to neuroinflammation and impaired insulin signaling." (PMID 39822993, 2025). "OLE is known for its hypoglycemic effects, which are attributed to its antioxidant potential, as well as the regulation of hyperglycemia through improved glucose-induced insulin release and increased peripheral glucose uptake." (PMID 41153863, 2025). "Type 1 diabetes (T1D) is an autoimmune disease characterized by the destruction of insulin-producing pancreatic β cells, which then results in inadequate insulin production and hyperglycemia." (PMID 41158127, 2025). "The physiological stress induced by pulmonary infection can lead to metabolic disorders, including altered hepatic glucose metabolism, increased peripheral insulin resistance, and hyperglycemia." (PMID 40260105, 2025). "Enhanced expression of PPARγ likely drives improved adipocyte differentiation, fatty acid oxidation, and insulin signaling in adipose and liver tissues, thereby attenuating dyslipidemia and hyperglycemia; these effects are amplified in the combined group." (PMID 41407819, 2025).
Hyperglycemia (continued). "Infants are exposed to hyperglycemia during pregnancy, and the resulting fetal hyperglycemia and upregulation of insulin production by the fetal pancreas are responsible for excessive fetal growth." (PMID 40348940, 2025). "Research reported that in adult pancreatic β-cells, short-term hyperglycemia enhanced the binding of PDX1 to the insulin gene, thereby increasing insulin mRNA levels." (PMID 40405977, 2025). "It was observed that these two patients experienced frequent episodes of hyperglycemia and hypoglycemia due to overfeeding and corrective insulin boluses." (PMID 41156246, 2025). "Myenteric neuronal insulin immunoreactivity was markedly influenced by hyperglycemia in our diabetic models." (PMID 40497986, 2025). "Sodium glucose cotransporters (SGLTs) occur mainly in the kidneys and play a key role in managing hyperglycaemia independently of insulin." (PMID 40422864, 2025). "This is followed by the onset of hyperglycemia, concurrent with a substantial decline in plasma insulin concentration." (PMID 40989847, 2025). "Concomitantly, the dysregulated trafficking of leukocytes into adipose tissue further exacerbates this pro-inflammatory shift, ultimately contributing to impaired insulin signalling and β-cell dysfunction, which can lead to hyperglycaemia." (PMID 41226484, 2025). "CEG analysis of our CGM-/POC-G pairs revealed minimal risk for inappropriate treatment of hypoglycaemia or hyperglycemia when using the CGMs studied, thus indicating that obtained CGM-G values are reliable for in-hospital insulin dosing." (PMID 40265636, 2025). "Metabolic dysregulation contributing to hyperglycemia involves multiple mechanisms, including reduced insulin secretion, impaired glucose uptake, and increased hepatic glucose production." (PMID 41012462, 2025). "The combination of hyperglycaemia and glucolipotoxicity (GLT) promotes loss of beta cell mass via beta cell apoptosis and/or dedifferentiation, and leads to decreased insulin production and impaired insulin gene expression." (PMID 39404845, 2025). "Older age emerged as a robust predictor, reflecting the cumulative burden of hyperglycemia, insulin resistance and vascular injury over time." (PMID 41438296, 2025). "It was demonstrated that MFLX induced hyperglycemia in diabetic rats, with a more pronounced reduction in serum insulin, GLP-1, and FGF15 levels than observed in normal rats." (PMID 40255568, 2025). "T1DM is recognized as an autoimmune disorder resulting from the pancreatic β-cells destruction, eventually leading to impaired insulin secretion and hyperglycemia." (PMID 41382274, 2025). "It involves the administration of once-a-day basal insulin and the administration of correction doses of a rapid-acting insulin to rectify hyperglycaemia." (PMID 40480914, 2025). "The patient admitted discontinuing long-acting insulin 2 to 3 years ago, relying solely on rapid-acting insulin in high doses to correct hyperglycemia." (PMID 40370476, 2025). "In animal models with a db gene knockout, hyperglycemia and the activity of gluconeogenesis-related enzymes cannot be effectively controlled, even with insulin intervention." (PMID 40703763, 2025). "An HFD induces hyperglycemia primarily by reducing insulin sensitivity in hepatic, adipose, and muscle tissues, leading to decreased glucose uptake and increased hepatic gluconeogenesis." (PMID 41011571, 2025). "For non-insulin-dependent patients, most of these factors relate to physiology, including postprandial hyperglycemia and the pancreas’s ability to respond to changes in blood glucose and regulate endogenous insulin levels." (PMID 41301738, 2025). "The SARS-CoV-2 can directly infect β-cells through binding to these receptors and induce β-cell damage, resulting in impaired insulin secretion, altered glucose metabolism, and hyperglycemia." (PMID 39902024, 2025).